HMGN2 (high mobility group nucleosomal binding domain 2)
Description:
Binds to the inner side of the nucleosomal DNA thus altering the interaction between the DNA and the histone octamer. May be involved in the process which maintains transcribable genes in a unique chromatin conformation (By similarity).
Synonyms: HMG17
Tractability: PROTAC: UniProt records ubiquitination sites on it; ubiquitination databases record sites on it; its protein half-life has been measured.
Gene: Protein-coding gene on chromosome 1 (26,472,013 to 26,478,209, forward strand). Ensembl gene ENSG00000198830.
Subcellular location: Nucleus; Cytoplasm
Subcellular location (Human Protein Atlas): Nucleoplasm; Nucleoli
Gene Ontology:
Molecular function: protein binding; RNA binding; chromatin binding; nucleosomal DNA binding
Biological process: antimicrobial humoral immune response mediated by antimicrobial peptide; killing of cells of another organism; chromatin organization
Cellular component: cytoplasm; extracellular region; nucleolus; nucleoplasm; nucleus; chromatin
Genetic constraint (gnomAD): Loss-of-function variants: 2 observed, 7.1 expected, observed/expected ratio (o/e) 0.28, 90% interval 0.11 to 0.89. That is too few expected variants to judge how well the gene tolerates losing a copy. Missense variants: 51 observed, 51.98 expected, observed/expected ratio (o/e) 0.98, 90% interval 0.78 to 1.24. Synonymous variants: 20 observed, 18.3 expected, observed/expected ratio (o/e) 1.09, 90% interval 0.77 to 1.58.
Homologues: Orthologues: chimpanzee HMGN2 (100% identical), tropical clawed frog hmgn2 (76% identical), zebrafish hmgn2 (63% identical). Paralogues in human: HMGN4 (87% identical), HMGN1 (61% identical), HMGN3 (61% identical).
Diseases named in the same sentence as HMGN2 in open-access papers:
HMGN2 is named in the same sentence as 35 diseases in open-access papers, as found by Europe PMC text mining. Sharing a sentence is not in itself a finding about the gene and the disease. The quoted sentences say what the papers report.
breast carcinoma (7 papers, 2019 to 2025). "In breast cancer, HMGN2 specifically promotes STAT5 accessibility to the promoter DNA by facilitating the dissociation of the linker histone H1." (PMID 40092489, 2025). "HMGN2 can inhibit the proliferation and cell cycle of tumor cells in breast cancer, oral squamous cell carcinoma, and osteosarcoma." (PMID 36568211, 2022). "Further analysis showed that the K2 residue of HMGN2 was deacetylated in primary breast tumors but highly acetylated in normal human breast tissue, implying that targeting HMGN2 deacetylation may be a viable treatment for this type of breast cancer." (PMID 31936777, 2020). "HMGN2 was also shown to promote breast cancer growth in response to prolactin." (PMID 31936777, 2020). "HMGN2 is an anti-tumor effector molecule of CD8+T cells, FOXO3 is a core tumor suppressor in breast cancer; downregulation of PPP2R5E is a common event in acute myeloid leukemia." (PMID 31540229, 2019). "In this system, HMGN2 reduces the binding of linker histone H1 to chromatin regulatory regions, thereby enhancing STAT5 accessibility to promoter DNA, ultimately leading to increased proliferation of breast cancer cells." (PMID 31936777, 2020).
osteosarcoma (5 papers, 2020 to 2025). A usually aggressive malignant bone-forming mesenchymal neoplasm, predominantly affecting adolescents and young adults. "The first most important gene for classifying the G1 state was HMGN2, and in prior studies over-expression of HMGN2 in osteosarcoma cells led to significantly higher number of cells in G0/G1." (PMID 38659838, 2025). "Some studies revealed that HMGN2 plays an anti-tumor role in osteosarcoma." (PMID 38225273, 2024). "To confirm that this lack of phenotype is not specific to osteosarcoma cells, we generated additional HMGN1/HMGN2-dKO cells in hTERT-immortalized human retinal pigment epithelial cells (RPE1) by CRISPR-Cas9-mediated genome editing." (PMID 32152397, 2020).
autoimmune disease (4 papers, 2014 to 2021). A disorder resulting from loss of function or tissue destruction of an organ or multiple organs, arising from humoral or cellular immune responses of the individual to their own tissue constituents. "HMGN2 is preferentially associated with chromatin subunits, and abnormal HMGN2 gene or protein expression is associated with development of neoplasms and autoimmune diseases." (PMID 25060707, 2014). "HMGN2 is preferentially associated with chromatin subunits, and abnormal HMGN2 gene or protein expression is associated with neoplasms and autoimmune diseases." (PMID 24348831, 2014).
microcephaly (4 papers, 2020 to 2024). A congenital or acquired developmental disorder in which the circumference of the head is smaller than normal for the person's age and sex. "Studies in mouse models have shown that HMGN2, the parental gene of HMGN2P3, is an important molecule involved in embryonic/postnatal brain development and that the loss of HMGN2 is associated with microcephaly." (PMID 33921034, 2021). "Indeed, high-mobility group nucleosomal binding domain 2 (HMGN2) was shown to be expressed in the SVZ and SGZ regions of adult mouse brain and loss of HMGN2 caused reduced self-renewal and increased differentiation of adult NSCs, which resulted in microcephaly." (PMID 38357000, 2024). "A recent study using a new line of Hmgn2−/− mice reports that mice lacking HMGN2 show reduced cortical surface and microcephaly, suggesting a role for HMGN2 in corticogenesis." (PMID 31936777, 2020).
gastric cancer (2 papers, 2024 to 2025). A primary or metastatic malignant neoplasm involving the stomach. "High rates of expression of HMGB3, HMGN1, HMGN2, HMGN3, and HMGN4 are shown in gastric cancer." (PMID 39062899, 2024).
glioma (2 papers, 2024 to 2025). A benign or malignant brain and spinal cord tumor that arises from glial cells (astrocytes, oligodendrocytes, ependymal cells). "This led to the conclusion that HMGN2 expression was positively associated with the grade of malignancy in gliomas." (PMID 40092489, 2025). "Further analysis of clinical data demonstrated that higher HMGN2 expression was associated with poor prognosis in patients with glioma." (PMID 40092489, 2025). "Under these circumstances, we conducted a bioinformatics analysis using public data to elucidate the molecular mechanisms of HMGN2 in glioma cells." (PMID 40092489, 2025). "In conclusion, alterations in the cell cycle induced by CDC20 play an important role in glioma cell proliferation resulting from HMGN2 knockdown." (PMID 40092489, 2025). "However, the effect of HMGN2 on gliomas and its underlying mechanisms remain unclear." (PMID 40092489, 2025). "Immunohistochemistry assays were performed to analyze the protein expression and subcellular localization of HMGN2 in a cohort of 60 paraffin-embedded archived glioma tissue samples (16 grade 2 glioma, 18 grade 3 glioma, and 26 grade 4 glioma)." (PMID 40092489, 2025). "Statistical analysis comparing the scores of HMGN2 staining across 60 archived glioma patient tissues showed that HMGN2 was widely expressed in gliomas and was significantly associated with the malignancy grade of the glioma." (PMID 40092489, 2025). "This study aimed to elucidate these uncertainties by demonstrating that HMGN2 significantly promotes the proliferation of glioma cells." (PMID 40092489, 2025). "In the current study, to elucidate the role of HMGN2 in glioma, we conducted a bioinformatics analysis which revealed significant up-regulation of HMGN2 expression in gliomas versus normal brain tissue." (PMID 40092489, 2025). "To evaluate the impact of HMGN2 on the proliferative capacity of glioma cells, we employed CCK8 and EdU assays to assess cell viability and DNA synthesis, respectively." (PMID 40092489, 2025). "To comprehensively evaluate the expression levels of HMGN2, we conducted qPCR and Western blot analyses on five glioma cell lines, including LN229, U-87 MG, A172, U118, and U251MG." (PMID 40092489, 2025). "In this study, we demonstrate that HMGN2 promotes the proliferation of glioma cells in vitro and in vivo and that glioma cells experience a slowdown in proliferation when HMGN2 is knocked down." (PMID 40092489, 2025). "Among the grade 4 glioma tissues, 20 (76.9%) exhibited high positive expression of HMGN2, whereas only two (12.5%) grade 2 glioma tissues showed highly positive staining." (PMID 40092489, 2025). "We found that the mRNA level of HMGN2 was significantly increased in high-grade gliomas compared with that in low-grade gliomas in the TCGA and CGGA datasets." (PMID 40092489, 2025). "It showed that HMGN2 expression was up-regulated in gliomas compared with normal brain tissue, with GBM (n = 163) exhibiting a more pronounced increase than low-grade gliomas (n = 518)." (PMID 40092489, 2025). "Based on the prominent pathway enrichments in both KEGG and GO analyses, we conclude that HMGN2 function in glioma tumorigenesis primarily involves the cell cycle." (PMID 40092489, 2025). "Additionally, our rescue experiments showed that restoration of CDC20 expression reversed the inhibitory effect of HMGN2 knockdown on glioma proliferation and reduced the proportion of cells in the G2/M phase." (PMID 40092489, 2025). "The results of the bioinformatics analysis were consistent with the flow cycle results, which indicated that HMGN2 could regulate proliferation in gliomas through the regulation of the G2/M phase of the cell cycle." (PMID 40092489, 2025). "Furthermore, HMGN2 expression positively correlated with glioma malignancy grade and poorer patient prognosis." (PMID 40092489, 2025).
glioma (continued). "We speculate that HMGN2 affects transcriptional activity by binding to histones in glioma cells, thereby increasing their acetylation levels and resulting in increased chromatin transcriptional activity." (PMID 40092489, 2025). "Overall, our study shows that HMGN2 enhances glioma cell proliferation both in vitro and in vivo." (PMID 40092489, 2025). "Therefore, it can be asserted that HMGN2 expression is significantly correlated with the prognosis of gliomas." (PMID 40092489, 2025). "Moreover, HMGN2 was correlated with cell cycle, proliferation, and DNA damage repair function in different types of gliomas." (PMID 40092489, 2025). "Taken together, these results suggest that HMGN2 could serve as a prognostic indicator and a new therapeutic target for gliomas." (PMID 40092489, 2025). "Moreover, the GSCs encompass not only encompasses known glioma genes, but also novel targets, such as HMGN2, TUBB4B, and ARL6IP1, that warrant further investigation." (PMID 39355251, 2024). "Taken together, these results demonstrated that HMGN2 and CDC20 expression were up-regulated in human glioma tissues, and we observed a clear correlation between CDC20 and HMGN2 expression." (PMID 40092489, 2025). "The overall survival of glioma patients from the TCGA and CGGA databases was significantly shorter when HMGN2 was up-regulated (P < 0.0001; median cutoff)." (PMID 40092489, 2025). "High-mobility group nucleosomal-binding domain 2 (HMGN2) participates in the epigenetic regulation of genes through histone modification and exhibits significant differential expression between glioma and normal tissues." (PMID 40092489, 2025). "The rescue experiment further showed that HMGN2 knockdown regulated the cell cycle by decreasing the level of CDC20, consequently attenuating the proliferative ability of glioma cells." (PMID 40092489, 2025). "In summary, these results indicated that HMGN2 and CDC20 are crucial for glioma progression and may serve as potential biomarkers for predicting the prognosis of patients with glioma." (PMID 40092489, 2025). "Finally, we identified HMGN2 and CDC20 as potential biomarkers and therapeutic targets for the treatment of glioma." (PMID 40092489, 2025). "In summary, our results show that HMGN2 is involved in the transcriptional regulation of CDC20 by modulating the acetylation level of H3K27 in the CDC20 promoter region, thereby affecting the cell cycle distribution and proliferative ability of gliomas." (PMID 40092489, 2025). "HMGN2 binds to histones and promotes the stability of H3K27ac acetylation in the cell division cycle 20 (CDC20) promoter region, enhancing the transcriptional activity of CDC20 and increasing the proliferation of glioma cells." (PMID 40092489, 2025). "HMGN2 and CDC20 expression levels are positively correlated in glioma tissues." (PMID 40092489, 2025).
oral squamous cell carcinoma (2 papers, 2014 to 2022). "The present study investigated the activity of the HMGN2 protein in the oral squamous cell carcinoma line, Tca8113." (PMID 24348831, 2014). "Tca8113 cells, an oral squamous cell carcinoma line, were treated with a variety of HMGN2 protein concentrations and cell growth was analyzed." (PMID 24348831, 2014). "In the present study, recombinant human HMGN2 protein was prepared and its antitumor activity was examined in the oral squamous cell carcinoma cell line, Tca8113." (PMID 24348831, 2014). "The results indicate that HMGN2 protein exhibits antitumor activity against oral squamous cell carcinoma and that HMGN2 may represent a candidate effector molecule for CTL or NK cells." (PMID 24348831, 2014). "The results of the current study indicated that the HMGN2 protein may inhibit the growth of oral squamous cell carcinoma and HMGN2 may represent an antitumor effector molecule of CTL or NK cells." (PMID 24348831, 2014).
adenoid cystic carcinoma (1 paper, 2014). A malignant tumor arising from the epithelial cells. "And our previous showed that HMGN2 significantly inhibits the growth of Tca8113 cells, adenoid cystic carcinoma cell-2 line (ACC-2), human lung adenocarcinoma epithelial cell line A549 and bladder cancer cell line T24, which acted by promoting apoptosis in vitro and in vivo." (PMID 25060707, 2014).
asthma (1 paper, 2020). "In addition, BHLHE22 and HMGN2, which contain bHLH and HMG-box protein domains, have been found to be highly associated with severe and moderate-to-severe asthma, respectively." (PMID 32512817, 2020).
autoimmune hemolytic anemia (1 paper, 2020). Autoimmune hemolytic anemia (AIHA) is an autoimmune disorder in which various types of auto-antibodies are directed against red blood cells causing their survival to be shortened and resulting in hemolytic anemia. "Leukemic B cells from patients with chronic lymphoblastic leukemia express HMGN2 on their surface; the HMGN2 variant acts as an autoantigen and contributes to the development of autoimmune hemolytic anemia." (PMID 31936777, 2020).
chronic myelogenic leukemia (1 paper, 2021). "The HMGN2 expression level in human leukemia cells from patients with chronic myelogenic leukemia was three times higher than normal leukocytes." (PMID 34298646, 2021).
embryonal carcinoma (1 paper, 2019). A non-seminomatous malignant germ cell tumor characterized by the presence of large germ cells with abundant cytoplasm resembling epithelial cells, geographic necrosis, high mitotic activity, and pseudoglandular and pseudopapillary structures formation. "The results of the present work demonstrate that the loss of HMGN1 or HMGN2 compromises the ability of embryonal carcinoma cells, and the neural stem cells derived from them, to self-renew accurately and maintain pluri/multipotency." (PMID 31831052, 2019). "We show that loss of Hmgn1 or Hmgn2 in pluripotent embryonal carcinoma cells leads to increased levels of spontaneous neuronal differentiation." (PMID 31831052, 2019). "We conclude that HMGN1 and HMGN2 maintain the identity of pluripotent embryonal carcinoma cells by optimising the pluripotency transcription factor network and protecting the cells from precocious differentiation." (PMID 31831052, 2019). "In this study, we have investigated the role of HMGN1 and HMGN2 in P19 embryonal carcinoma stem cells." (PMID 31831052, 2019). "CRISPR mutagenesis was used to create clonal derivatives of murine P19 embryonal carcinoma cells in which HMGN1 or HMGN2 protein expression was abolished." (PMID 31831052, 2019).
heart failure (1 paper, 2025). Inability of the heart to pump blood at an adequate rate to meet tissue metabolic requirements. "The results showed that, compared to normal samples, HMGN2, HTRA1, LTBP2, and MFAP4 were significantly upregulated in heart failure, while MYH6 was downregulated (p < 0.001)." (PMID 40406620, 2025).
influenza (1 paper, 2019). An acute viral infection of the respiratory tract, occurring in isolated cases, in epidemics, or in pandemics; it is caused by serologically different strains of viruses (influenzaviruses) designated A, B, and C, has a 3-day incubation period, and usually lasts for 3 to 10 days. "It has been demonstrated that IFITM proteins can be the antiviral restriction factors for influenza It has been demonstrated that IFITM proteins can be as antiviral restriction factors for inhibiting influenza A virus replication, which suggested a possible contribution of HMGN2 in innate immunity." (PMID 31596045, 2019).
lung carcinoma (1 paper, 2022). "The inhibition rate of tumor metastasis in mice with lung cancer injected with IIF2 is 50–60%, further suggesting that HMGN2 can suppress tumor metastasis." (PMID 36568211, 2022).
lung squamous cell carcinoma (1 paper, 2020). "Loss of HMGN2 is frequently observed in lung squamous cell carcinoma patients with history of smoking as compared to non-smokers." (PMID 33251127, 2020).
periodontitis (1 paper, 2024). An acute or chronic inflammatory process that affects the tissues that surround and support the teeth. "Other DAMPs such as HSP70, cyclophilin A, amyloid beta, high mobility group nucleosomal-binding domain 2 (HMGN2) and IL-1 were also found to be highly expressed at the site of periodontitis." (PMID 39555084, 2024).